ZXDC (ZXD family zinc finger C)
Description:
Cooperates with CIITA to promote transcription of MHC class I and MHC class II genes.
Synonyms: ZXDL; MGC11349; FLJ13861
Tractability: PROTAC: UniProt records ubiquitination sites on it; ubiquitination databases record sites on it.
Gene: Protein-coding gene on chromosome 3 (126,437,601 to 126,475,993, reverse strand). Ensembl gene ENSG00000070476.
Subcellular location: Nucleus
Subcellular location (Human Protein Atlas): Nucleoli
Gene Ontology:
Molecular function: C2H2 zinc finger domain binding; LRR domain binding; protein binding; transcription coactivator activity; transcription coregulator activity
Biological process: positive regulation of DNA-templated transcription; regulation of transcription by RNA polymerase II
Cellular component: nucleus
Genetic constraint (gnomAD): Loss-of-function variants: 58 observed, 60.69 expected, observed/expected ratio (o/e) 0.96, 90% interval 0.77 to 1.19. The synonymous counts are far from expectation, so gnomAD's model fits this gene poorly and the ratio says little. Missense variants: 1,133 observed, 1,053.6 expected, observed/expected ratio (o/e) 1.08, 90% interval 1.02 to 1.13. Synonymous variants: 561 observed, 456.5 expected, observed/expected ratio (o/e) 1.23, 90% interval 1.15 to 1.32.
Homologues: Orthologues: chimpanzee ZXDC (99% identical), macaque ZXDC (98% identical), dog ZXDC (78% identical), rat Zxdc (77% identical), mouse Zxdc (77% identical), pig ZXDC (70% identical), guinea pig ZXDC (66% identical), rabbit ZXDC (66% identical), tropical clawed frog zxdc (52% identical), zebrafish si:dkey-156n14.3 (45% identical), Drosophila melanogaster ci (14% identical), Drosophila melanogaster lmd (13% identical), and 5 more. Paralogues in human: ZXDB (53% identical), ZXDA (52% identical), GLI2 (20% identical), GLI3 (18% identical), GLIS3 (15% identical), GLI1 (14% identical), GLIS1 (13% identical), ZIC5 (12% identical), GLIS2 (12% identical), ZIC2 (11% identical), ZIC3 (11% identical), ZIC1 (11% identical), and 2 more.
Diseases named in the same sentence as ZXDC in open-access papers:
ZXDC is named in the same sentence as 2 diseases in open-access papers, as found by Europe PMC text mining. Sharing a sentence is not in itself a finding about the gene and the disease. The quoted sentences say what the papers report.
lung carcinoma (1 paper, 2021). "miRNA-regulated gene ZXDC was unique to lung cancer participants compared to healthy non-smokers, targeted by two over-expressed miRNAs." (PMID 34071592, 2021).
ZXDC also shares sentences with these, for which no sentence is quoted: cancer (1 paper).